SPHK1 (sphingosine kinase 1)
Diseases named in the same sentence as SPHK1 in open-access papers (continued):
Sharing a sentence is not in itself a finding about the gene and the disease.
glioblastoma (33 papers, 2009 to 2025). The most malignant astrocytic tumor (WHO grade IV). "The high mRNA level of SphK1 is linked with high IL-1 expression in the U373 glioblastoma cell line and primary human astrocytes." (PMID 33920887, 2021). "In an interesting contrast to these findings, expression of the S1P1 receptor suppresses glioblastoma growth and malignancy, despite the established association of SPHK1 with increased glioblastoma malignancy." (PMID 24970218, 2014). "It is also upregulated in several types of cancer one of them being glioblastoma, where an elevated level of Sphk1 is associated with poor prognosis." (PMID 22384097, 2012). "In addition, increased S1P in glioblastoma multiforme tissues is associated with increased SPHK1 and decreased expression of S1P phosphatase (SGPP2)." (PMID 26493335, 2015). "Collectively, our findings demonstrate that TMZ-induced autophagy-dependent ENO1 secretion activates two pivotal signaling axes, TLR4-mediated PI3K/Akt and SPHK1/S1P pathways, to drive glioblastoma malignancy." (PMID 41353343, 2025). "A relationship between high SPHK1 and poor patient outcomes has been observed in bladder, breast, gastric, glioblastoma and oesophageal cancers." (PMID 40356021, 2025). "The human cytomegalovirus-encoded G protein-coupled receptor (GPCR), US28, was reported to promote U251 glioblastoma malignancy by stimulating SPHK1 function to release more S1P, which signals via S1PR1 using in vitro assays." (PMID 38894892, 2024). "Sphk1 expression is upregulated in peripheral blood monocytes of patients with sepsis, and studies have found that Sphk1 promotes inflammation and proliferation of glioblastoma through the NF-κB/IL-6/STAT3 signaling pathway." (PMID 38482014, 2024). "For example, SK1-I, a sphingosine analogue and competitive inhibitor of SPHK1, attenuated glioblastoma growth and proliferation in cell lines and xenograft models." (PMID 36361531, 2022). "Several studies illustrated that the inhibition of SPHK1 results in a decrease in cell viability following the temozolomide treatment in temozolomide-resistant glioblastoma cells." (PMID 35004331, 2021). "Kapitonov found that SK1-I reduced the growth, migration, and invasion of several glioblastoma multiforme (GBM) cell lines by using SphK1 inhibition." (PMID 27129720, 2016). "As previously reported, mRNA level and SphK1 activity were markedly decreased (60–90% range) in all cancer cell lines (prostate PC-3, lung A549, glioblastoma U87, ccRCC CAKI-1 and A498) treated with siSphK1 compared with scrambled siRNA (siScr)." (PMID 26974204, 2016). "In an early study, Van Brocklyn JR found that RNA interference of SphK2 expression inhibited glioblastoma cell proliferation more potently than did SphK1 knockdown." (PMID 27129720, 2016). "In regard to the role of SPHK1 in tumour angiogenesis, compound 1a potently inhibited glioblastoma-induced angiogenesis in an in vitro co-culture system, supporting studies with siRNA and the less potent inhibitor SK1-I." (PMID 24970218, 2014). "Further, silencing the endogenous expression of SPHK1 in glioblastoma cells and breast cancer cells leads to cell cycle arrest." (PMID 20846391, 2010). "Moreover, Van Broocklin demonstrated that a high expression level of SphK1 correlates with poor survival in patients affected by glioblastoma multiforme." (PMID 39940821, 2025). "The expression of SphK1 in glioblastoma is inversely correlated with patient survival." (PMID 41303601, 2025). "Increased level of S1P produced by SphK1 is related to the oncogenic effects regulated by S1P and this is correlated to high level of SphK1 in glioblastoma cell lines; the inhibition of SphK1 have been shown to decrease xenografts and human glioblastoma cell growth." (PMID 41303601, 2025). "Interestingly, in a clinical study with patients with glioblastoma, a correlation between SphK1 and poor survival was observed." (PMID 34357010, 2021).
glioblastoma (continued). "Interestingly, knockdown of SphK2 presented more potent inhibition of glioblastoma cell proliferation than SphK1 knockdown." (PMID 34305532, 2021). "Interestingly, a correlation between SphK1 and poor survival has been observed in a clinical study with patients with glioblastoma." (PMID 34202192, 2021). "In addition, chemical or transcriptional down-regulation of SphK1 induces apoptosis and suppresses the growth of human glioblastoma cells and xenografts." (PMID 34202192, 2021). "Moreover, selective inhibition of SphK1 or SphK2 with siRNA in U-1242 and U-87MG glioblastoma cell lines showed an inhibition of cell proliferation, with more potent action when SphK2 was silenced." (PMID 34357010, 2021). "Moreover, specific inhibition of SphK1 or SphK2 resulted in a cell-cycle arrest in U-1242 and U-87MG glioblastoma." (PMID 34202192, 2021). "In addition, high levels of the SPHK1 enzyme and its downstream product, S1P, correlate with poor survival of glioblastoma patients, and this unusual enhancement of neural cell invasion requires upregulation of the matricellular protein CCN1/Cyr61." (PMID 21936950, 2011). "In our study, LH-EGFR signaling-activated SphK1/2 in granulosa cells to increase S1P levels, consistent with a previous study showing that EGF enhances S1P synthesis and secretion in glioblastoma stem cells." (PMID 36396932, 2022). "SphK1 inhibition by SK1-I suppresses LN229 and U373 glioblastoma cell lines by initiating apoptosis and reducing tumor vascularization." (PMID 33920887, 2021). "EGF is known to stimulate SPHK1 expression and activity, as does expression of EGFRvIII, which is a truncated and constitutively active form of EGFR commonly found in glioblastomas." (PMID 24970218, 2014). "Beside glioblastoma patient samples, we isolated glioblastoma cells from freshly resected tumor tissue of three different patients and analyzed the expression of S1P1-5, SphK1 and 2, SGPP1 and 2 as well as SGPL1 by quantitative RT-PCR." (PMID 26887055, 2016).
Obesity (30 papers, 2013 to 2024). Accumulation of substantial excess body fat. "It would be important to understand the precise molecular mechanisms by which the derangements of sphingolipid metabolism induced by Sphk1 deficiency result in impaired lipophagy, for developing a new anti-obesity therapeutic strategy to target lipophagy." (PMID 37751791, 2023). "Obesity and high-fat diet are the main cause for increased expression of the S1P and SPHK1, and targeting the SPHK1/S1P/S1PR1 decreases key proinflammatory cytokines, macrophage infiltration, and tumor progression." (PMID 34283088, 2021). "In white adipose tissue, SphK1 prevents obesity-associated diabetes, whereas the adipose-specific role of SphK2 remains elusive." (PMID 33633691, 2020). "Alternatively the diet itself is strongly associated with obesity and can have a considerable impact on metabolic regulation, possibly affecting Sphk1 regulation in M1 and M2 macrophages." (PMID 28753653, 2017). "In these experimental scenarios, inhibition of SphK1 was suggested as a therapeutic tool for the prevention and treatment of inflammation associated with obesity and type 2 diabetes." (PMID 25866760, 2015). "Therefore, Sphk1 are implicated in several metabolic diseases, such as obesity, diabetes, and cardiovascular disease." (PMID 33208918, 2020). "The results suggest that the K27Q/K29Q mutations of Sphk1 could serve a beneficial role in regulating lipid and glucose metabolism and thereby protect mice from obesity and its associated pathologies." (PMID 33208918, 2020). "The K27Q/K29Q mutations of Sphk1 in mice resulted in amelioration of HFD-induced obesity." (PMID 33208918, 2020). "Collectively, this study provided evidence that the K27Q/K29Q mutations of Sphk1 could have a protective role in preventing obesity and the related metabolic diseases." (PMID 33208918, 2020). "Studies show that obesity increases SphK1 expression in adipose tissue macrophages of both M1 and M2 phenotypes." (PMID 39777222, 2024). "The expression of obesity-related mediators (SphK1 and S1PR1) is enhanced in metastatic lesions of syngeneic and spontaneous breast tumor obese mice, along with elevated levels of TNF-α and IL-6." (PMID 36880535, 2023). "We found increased S1P production and up-regulated SPHK1 expression in human lymphomas and in obesity-lymphoma mice." (PMID 36600310, 2023). "Obesity enhances the expression of sphingosine kinase 1 (SphK1), the enzyme that produces S1P and its receptor S1PR1." (PMID 36670988, 2023). "In human study, up-regulated S1P/SPHK1 was found in human lymphomas, while obesity negatively impacted progression-free survival and overall survival in lymphoma patients." (PMID 36600310, 2023). "A growing body of research emphasizes the role of SPHK1 in regulating glucose and fat metabolism and suggests its potential use as a promising therapeutic target for obesity and T2DM." (PMID 37432552, 2023). "Targeting the SphK1/S1P/S1PR1 axis with specific drugs can reduce tumor progression caused by key proinflammatory cytokines, macrophage infiltration, and obesity." (PMID 33747044, 2021). "To get more insight in the regulation of Sphk1 expression and its activity in obesity, we systematically tested above conditions using the mouse macrophage-like RAW264.7 cells." (PMID 28753653, 2017). "Indeed, obesity-induced breast tumors increase SphK1 and secrete S1P, which promotes macrophage recruitment through S1PR1 in lung premetastatic niches." (PMID 36670988, 2023). "Notably, we found that resveratrol showed the potential effects on not only blockage of S1P/SPHK1 signaling but also intervention of macrophage polarization in the tumor microenvironment of obesity-lymphoma." (PMID 36600310, 2023). "Based on this, we suspect that inhibition of SPHK1 by CBD may be considered as a potential therapeutic approach to restoring normal insulin activity in obesity." (PMID 35628194, 2022).
Obesity (continued). "Obesity was found to increase SphK1 expression in AT macrophages of both M1 and M2 phenotypes." (PMID 32668665, 2020). "Among the two forms of SphK (SphK1 and SphK2), SphK1 expression is increased in insulin sensitive tissues but also in islets of Langerhans from mice under high fat diet (HFD) and in T2D patients, suggesting that this enzyme is involved in the onset of T2D associated with obesity." (PMID 37628901, 2023). "Targeting the SphK1/S1P/S1PR1 axis mediated by lipid metabolism attenuates key pro-inflammatory cytokines and macrophage infiltration as well as obesity-induced tumor progression." (PMID 36880535, 2023). "Lastly, we explored the biological role of Sphk1 activity in macrophages undergoing a high FFA pressure, hence mimicking local adipocyte-derived FFA elevation in obesity." (PMID 28753653, 2017). "SphK1 affects the migration and activation of inflammatory cells like macrophages and lymphocytes, as well as the production of cytokines including tumor necrosis factor-alpha (TNF-α), interleukin-6 (IL-6), and IL-10, thus serving both pro-inflammatory and anti-inflammatory functions in obesity." (PMID 39777222, 2024).
gastric cancer (29 papers, 2011 to 2025). A primary or metastatic malignant neoplasm involving the stomach. "Associations between SphK1 and the clinical stage of gastric cancer have also been confirmed in several other studies." (PMID 34831211, 2021). "Overexpression of SphK1 in human peritoneal mesothelial cells is linked to LC3B expression (an autophagy protein marker) which regulates human peritoneal mesothelial cells autophagy via TGF-β1 secretion in gastric cancer peritoneal dissemination progression." (PMID 33920887, 2021). "We also demonstrated that the anti-apoptotic effect of SphK1 on gastric cancer cells is associated with the activation of the Akt/FOX3a pathway, suggesting that inhibition of SphK1 may represent a novel approach to the treatment of gastric cancer." (PMID 25109605, 2014). "Similarly, in gastric cancer, high SPHK1 was associated with metastasis and venous invasion." (PMID 40356021, 2025). "SPHK1 enhances the peritoneal spread of gastric cancer by regulating autophagy of peritoneal mesenchymal cells, and SPHK1 is targeted by microRNA-506-3p to inhibit osteosarcoma cell autophagy and invasion." (PMID 38135696, 2024). "SPHK1 also modulates autophagy in human peritoneal mesothelial cells (HPMCs) and plays a role in the progression of gastric cancer peritoneal dissemination (GCPD)." (PMID 37190124, 2023). "SPHK1 expression was directly related to LC3 expression in 120 human samples from gastric cancer peritoneal tissue." (PMID 37190124, 2023). "The SPHK1-induced autophagy in HPMCs increased the invasive capability of gastric cancer cells, whereas SPHK1 knockdown inhibited autophagy." (PMID 37190124, 2023). "In gastric cancer, S1P, SphK1 synthesizes binds to S1PR2 and transactivates two potent RTKs, EGFR and c-Met." (PMID 33920887, 2021). "SphK1 repression diminishes the ability to resist UV-induced cell death, implying SphK1 contribution in sustaining the unwanted survival of gastric cancer cells under radiotherapy." (PMID 33920887, 2021). "It has been demonstrated that SphK1 contributes to apoptosis resistance via regulating the Akt/FOXO3a/Bim pathway in glioma cells and gastric cancer cells, leading to the downregulation of Bim as a pro-apoptotic protein." (PMID 35201458, 2021). "In NCI-N87 cells, a gastric cancer cell line with a highly dysregulated genome, synthetic lethality between SPHK1 and CDH1 was abrogated, demonstrating the importance of genetic background to SPHK1′s synthetic lethality." (PMID 35008266, 2021). "miR-124 down-regulated SphK1 by binding to 3′untranslated regions (3′UTRs) of SPHK1 and subsequently suppressed the tumorigenicity of gastric cancer cells." (PMID 34831211, 2021). "Spiegel’s group showed that LPAR1 and EGFR act in concert to mediate the upregulation of sphingosine kinase 1 (SphK1), which promotes invasion and motility in gastric carcinoma." (PMID 34440828, 2021). "More reports show that miR-124-3p reduces gastric cancer cell proliferation via targeting SPHK1 and suppresses cervical cancer tumorigenesis through targeting AEG-1." (PMID 33094104, 2020). "In that regard, miR-506 suppressed tumor angiogenesis through targeting SphK1 mRNA in liver cancer, while miR-124 downregulated SphK1 and inhibited proliferation of gastric cancer cells." (PMID 27800303, 2016). "We examined the relationship between SPHK1 protein expression measured by IHC, and cisplatin resistance in an independent panel of 21 gastric cancer cell lines." (PMID 26493335, 2015). "High SPHK1 protein correlated with resistance to cisplatin (IC50) in an independent gastric cancer cell line panel and with survival of patients treated with chemotherapy prior to surgery but not in patients treated with surgery alone." (PMID 26493335, 2015). "Safingol a SPHK1 inhibitor, was cytotoxic as a single agent and acted synergistically with cisplatin in gastric cancer cell lines." (PMID 26493335, 2015).
gastric cancer (continued). "Here, we demonstrated that SphK1 indeed plays an important role in the anti-apoptotic state of gastric cancer cells." (PMID 25109605, 2014). "In the present study, we used known differential effects of UV irradiation on human MGC-803 gastric cancer cells to determine their effect on SphK1 activity." (PMID 25109605, 2014). "Taken together, our study supports the theory that SphK1 confers resistance to apoptosis in gastric cancer cells via the Akt/FoxO3a/Bim pathway." (PMID 25109605, 2014). "In the present study, we reported the role of SphK1 in the sensitization of radiation-resistant MGC-803 gastric cancer cells to UV-induced apoptosis." (PMID 25109605, 2014). "In contrast, Bim level was significantly upregulated in SphK1-knockdown gastric cancer cells, suggesting a specific regulatory role of SphK1 in cell apoptosis." (PMID 25109605, 2014). "The phosphorylation levels of Akt and FoxO3a were indeed increased in ectopically SphK1-transduced gastric cancer cells." (PMID 25109605, 2014). "In order to demonstrate the expression levels of SphK1 in the engineered MGC-803 gastric cancer cells, western blotting and real-time PCR analysis were performed." (PMID 25109605, 2014). "Collectively, the present study suggests a novel signaling cascade that links SphK1 to the antiapoptotic property of cancer cells and provides novel therapeutic targets against gastric cancer." (PMID 25109605, 2014). "Ectopic expression of SphK1 in MGC-803 gastric cancer cells markedly enhanced their resistance to UV irradiation, whereas silencing endogenous SphK1 with shRNAs weakened this ability." (PMID 25109605, 2014). "ERK1 as an important mediator of lysophosphatidic acid signaling leading to upregulation of sphingosine kinase 1 (SphK1) and point to SphK1 and sphingosine-1-phosphate production as potential therapeutic targets in gastric cancer." (PMID 23922976, 2013). "SphK1 was also shown to be elevated in gastric cancer tissues, correlating with poor prognosis." (PMID 35158806, 2022). "In gastric cancer cells, miR-124 targeted and silenced SphK1 to inhibit proliferation." (PMID 33465049, 2021). "In gastric cancer, it downregulates SPHK1 expression via direct targeting of its 3′-UTR." (PMID 35201458, 2021). "SphK1 overexpression suppresses the expression level of FoxO3a, thereby decreases Bim, a pro-apoptotic protein expression, resulting in enhanced apoptotic resistance in gastric cancer cells." (PMID 33920887, 2021). "As high SphK1 correlates with resistance to cisplatin in gastric cancer, safingol was used synergistically with cisplatin to restore the efficacy of the chemotherapy in gastric cancer cells." (PMID 32722626, 2020). "CEBPB is involved in transcriptional up-regulation of SphK1 by LPA in gastric cancers." (PMID 24597747, 2014). "Similarly, the result of Annexin V-binding assay was consistent with the TUNEL assay, suggesting that SphK1 promoted resistance of gastric cancer cells against radiation-induced apoptosis." (PMID 25109605, 2014). "Based on these previous findings, we hypothesized that SphK1 may be involved in gastric cancer tumorigenesis via regulation of the Akt/FoxO3a signaling pathway." (PMID 25109605, 2014). "Additionally, many studies also focused on roles of SphK1 in gastric cancer." (PMID 34831211, 2021). "We previously reported that sphingosine kinase 1 (SphK1), an enzyme that catalyzes the production of sphingosine- 1-phosphate (SIP), is upregulated in human gastric cancer and predicts poor clinical outcome." (PMID 25109605, 2014). "The available evidence demonstrated that SphK1 protein expression levels were increased in human gastric cancer tissues, in comparison to the surrounding noncancerous specimens." (PMID 34831211, 2021). "SPHK1 activity and levels of S1-P have been demonstrated to be involved in resistance to cytotoxic and targeted agents in a variety of cancer types, although not in esophageal or gastric cancer drug resistance." (PMID 26493335, 2015).